PIGA (phosphatidylinositol glycan anchor biosynthesis class A)
Description:
Catalytic subunit of the glycosylphosphatidylinositol-N-acetylglucosaminyltransferase (GPI-GnT) complex that catalyzes the transfer of N-acetylglucosamine from UDP-N-acetylglucosamine to phosphatidylinositol and participates in the first step of GPI biosynthesis.
Synonyms: PIG-A; GPI3; MCAHS2; NEDEPH; PNH1
Tractability: Antibody: UniProt predicts a signal peptide or a membrane-spanning region. PROTAC: ubiquitination databases record sites on it.
Gene: Protein-coding gene on chromosome X (15,319,452 to 15,335,554, reverse strand). Ensembl gene ENSG00000165195.
Subcellular location: Rough endoplasmic reticulum membrane
Pathways (Reactome):
Metabolism of proteins: Synthesis of glycosylphosphatidylinositol (GPI)
Gene Ontology:
Molecular function: protein binding; phosphatidylinositol N-acetylglucosaminyltransferase activity; UDP-glycosyltransferase activity; glycosyltransferase activity
Biological process: GPI anchor biosynthetic process
Cellular component: endoplasmic reticulum membrane; glycosylphosphatidylinositol-N-acetylglucosaminyltransferase (GPI-GnT) complex; membrane; rough endoplasmic reticulum membrane
Gene-disease validity (ClinGen):
ClinGen rates the evidence that PIGA causes each of these diseases.
complex neurodevelopmental disorder (X-linked): Definitive. A disorder that involves more than one phenotype associated with the central nervous system, including but not limited to intellectual disability, autism, and seizures (epilepsy).
Homologues: Orthologues: chimpanzee PIGA (99% identical), macaque PIGA (95% identical), pig PIGA (93% identical), rabbit PIGA (90% identical), rat Piga (89% identical), mouse Piga (88% identical), guinea pig PIGA (85% identical), tropical clawed frog piga (79% identical), zebrafish piga (73% identical), Drosophila melanogaster PIG-A (48% identical), Caenorhabditis elegans piga-1 (47% identical). Paralogues in human: ALG11 (14% identical), ALG2 (13% identical), GLT1D1 (11% identical).
Diseases named in the same sentence as PIGA in open-access papers:
PIGA is named in the same sentence as 100 diseases in open-access papers, as found by Europe PMC text mining. Sharing a sentence is not in itself a finding about the gene and the disease. The quoted sentences say what the papers report.
paroxysmal nocturnal hemoglobinuria (82 papers, 2009 to 2026). Paroxysmal nocturnal hemoglobinuria (PNH) is an acquired clonal hematopoietic stem cell disorder characterized by corpuscular hemolytic anemia, bone marrow failure and frequent thrombotic events. "Paroxysmal nocturnal hemoglobinuria (PNH) is a rare disease characterized by acquired mutation in the PIGA gene in hematopoietic stem cells making red blood cells susceptible to complement mediated hemolysis." (PMID 37854608, 2023). "Here, paroxysmal nocturnal hemoglobinuria patients have an X-linked acquired Phosphatidylinositol N-acetylglucosaminyltransferase subunit A (PIGA) mutation." (PMID 37275911, 2023). "The PIGA gene has been reported to be linked to paroxysmal nocturnal hemoglobinuria, a disease characterized by hemolysis and thrombosis." (PMID 35966924, 2022). "Paroxysmal nocturnal hemoglobinuria (PNH) is an acquired hematologic disorder caused by somatic mutations of the PIGA gene in hematopoietic stem cells." (PMID 33804461, 2021). "PIGA:p.Leu359PhefsTer19, associated with the glycosyl transferases group 1 family, is likely pathogenic causing paroxysmal nocturnal hemoglobinuria." (PMID 33481921, 2021). "In AA the genomic landscape is more shaded, with less MDS-associated and more frequent typical paroxysmal nocturnal hemoglobinuria (PNH)-related PIGA mutations, while in hypoplastic MDS the picture is somehow in between MDS and AA." (PMID 34659257, 2021). "GPI-anchors regulate the erythrocyte-stimulatory/lytic cycle, and hemolytic anemia is associated with paroxysmal nocturnal hemoglobinuria, caused by somatic PIGA variants." (PMID 32635232, 2020). "Paroxysmal nocturnal hemoglobinuria (PNH) is an acquired disorder of hematopoiesis characterized by a somatic mutation in the PIGA gene that prevents or impairs the synthesis of glycosylphosphatidylinositol (GPI) anchors." (PMID 28629435, 2017). "Pathogenic mutations in PIGA cause paroxysmal nocturnal hemoglobinuria (MIM 300818) and multiple congenital anomalies-hypotonia-seizures syndrome 2 (MCAHS2, MIM 300868)." (PMID 27353043, 2016). "Paroxysmal nocturnal hemoglobinuria (PNH) is a clonal hematopoietic stem cell disorder caused by a somatic mutation in phosphatidylinositol N-acetylglucosaminyltransferase subunit A (PIGA), whose gene product is required for the synthesis of glycosylphosphatidylinositol (GPI) anchors." (PMID 39910008, 2025). "One condition associated with aplastic anemia is paroxysmal nocturnal hemoglobinuria (PNH) which arises from the somatic mutation of the gene encoding the phosphatidylinositol N-acetylglucosaminyltransferase subunit (PIGA) and results in complement-mediated hemolysis." (PMID 37627314, 2023). "The etiology of a rare hematological disorder termed paroxysmal nocturnal hemoglobinuria (PNH) is the clonal expansion of hematopoietic stem cells carrying somatic loss-of-function mutations in PIGA, which encodes an enzyme pivotal for the biosynthesis of GPI-anchors." (PMID 34490277, 2021). "Paroxysmal nocturnal hemoglobinuria (PNH) originates from hematopoietic stem cells (HSCs) harboring somatic mutations in the phosphatidylinositol glycan class A (PIGA) gene." (PMID 42020783, 2026). "Paroxysmal Nocturnal Hemoglobinuria (PNH) is a rare acquired clonal blood disorder caused by mutations in the PIGA gene, leading to complement‐mediated hemolysis." (PMID 40661733, 2025). "Paroxysmal nocturnal hemoglobinuria (PNH) is an acquired hematopoietic stem cell disorder, resulting from a somatic mutation in the X-linked gene phosphatidylinositol glycan class A (PIGA) which leads to the expansion of hematopoietic stem cell clones." (PMID 38702811, 2024). "As a result of a somatic mutation in the PIGA (phosphatidylinositol glycan class A) gene on chromosome X, people with paroxysmal nocturnal hemoglobinuria (PNH) lack a certain protein." (PMID 39295707, 2024).
paroxysmal nocturnal hemoglobinuria (continued). "Among them, somatic mutations of the PIGA gene have been reported in patients with paroxysmal nocturnal hemoglobinuria (PNH), while germline mutations have long been considered to be lethal." (PMID 39767685, 2024). "While germline mutants in this pathway remain poorly understood, recent research in Paroxysmal Nocturnal Hemoglobinuria (PNH) caused by somatic mutations in PIGA has revolutionized our understanding of GPI deficiency related pathology." (PMID 31232685, 2019). "Somatic PIGA mutations cause paroxysmal nocturnal hemoglobinuria (PNH) (MIM 300818), an acquired complement‐mediated hemolytic disease resulted from loss of GPI‐anchored CD55 and CD59 on erythrocytes." (PMID 29974678, 2018). "The best described probably being paroxysmal nocturnal hemoglobinuria (PNH), a syndrome that is most commonly caused by mutations in phosphatidylinositol glycan A (PIGA)." (PMID 24782851, 2014). "Paroxysmal nocturnal hemoglobinuria (PNH) is a rare, acquired clonal hematological disorder caused by somatic PIGA mutations, resulting in deficiency of glycosylphosphatidylinositol‐anchored complement regulatory proteins and complement‐mediated intravascular hemolysis." (PMID 41268092, 2025). "PIGA, an enzyme involved in GPI anchor biosynthesis, has been implicated in juvenile hemochromatosis and paroxysmal nocturnal hemoglobinuria." (PMID 39935693, 2024). "Paroxysmal nocturnal hemoglobinuria (PNH), an acquired clonal blood disorder linked to somatic variants of the phosphatidylinositol glycan (PIG) type A (PIGA) gene, was the first disorder known to result from disruption of a GPI gene." (PMID 38790248, 2024). "In the context of acquired BMF syndromes, paroxysmal nocturnal hemoglobinuria (PNH) is a clonal disease caused by a somatic mutation in the PIGA-gene resulting in the deficiency of GPI-anchored proteins (such as CD55 and CD59) and leads to erythrocytes unable to control complement activation." (PMID 36439498, 2022). "According to DECIPHER database, the mutations of PIGA gene may result in paroxysmal nocturnal hemoglobinuria (PNH) and multiple congenital anomalies-hypotonia-seizures syndrome-2(MCAHS2)." (PMID 35713440, 2022). "Germline PIGA mutations give rise to an X-linked MCAHS2, and somatic mutations in bone marrow cells result in paroxysmal nocturnal hemoglobinuria." (PMID 32019583, 2020). "Paroxysmal nocturnal hemoglobinuria (PNH) is a rare clonal disorder of hematopoietic stem cells, characterized by a somatic mutation of the phosphatidylinositol glycan-class A (PIGA)." (PMID 30867971, 2019). "Paroxysmal nocturnal hemoglobinuria (PNH; OMIM 300818) is a rare disease, which is caused by a mutation in the PIGA gene on chromosome Xp22." (PMID 31113379, 2019). "Mutations in another enzyme in the GPI synthesis pathway, PIGA, cause paroxysmal nocturnal hemoglobinuria, in which hematopoietic stem cells produce RBCs lacking CD55 and CD59, 2 surface proteins that prevent RBCs hemolysis." (PMID 41431006, 2025). "Paroxysmal nocturnal hemoglobinuria (PNH) is an acquired and clonal disease characterized by hemolytic anemia, bone marrow failure, thrombophilia, and multiorgan damage, which results from the mutation of the X‐linked PIGA gene." (PMID 37647437, 2023). "The first disorders to be described in association with deficiencies of the GPI-anchor biosynthesis pathway were paroxysmal nocturnal haemoglobinuria (PNH), caused by somatic mutations in PIGA, in haemopoietic cells, and inherited GPI deficiency caused by a hypomorphic promoter mutation in PIGM." (PMID 26293662, 2015). "Until recently, only somatic PIGA mutations had been reported in patients with paroxysmal nocturnal hemoglobinuria (PNH), while germline mutations had not been observed, and were suspected to result in lethality." (PMID 25885527, 2015). "Paroxysmal nocturnal hemoglobinuria (PNH) is an acquired, non-malignant clonal hematopoietic stem cell disorder caused by somatic mutations in the PIGA gene." (PMID 41450399, 2025).
paroxysmal nocturnal hemoglobinuria (continued). "Paroxysmal nocturnal hemoglobinuria (PNH) is acquired clonal stem cell disorder due to somatic mutation in the PIGA gene characterized by hematopoietic stem cells lacking or having reduced glycosylphosphatidylinositol (GPI)-anchored proteins on their surfaces." (PMID 39898138, 2024). "Phosphatidylinositol glycan anchor biosynthesis class A (PIGA) is a key enzyme in GPI anchor biosynthesis, somatic mutations or genetic variants of which have been associated with paroxysmal nocturnal hemoglobinuria (PNH), or PIGA deficiency, respectively." (PMID 29974678, 2018). "Paroxysmal nocturnal hemoglobinuria (PNH) is a rare, X-linked blood disorder in which red blood cells lack the GPI-APs CD55 and CD59 due to somatic mutations in a gene (phosphatidylinositol glycan class A, PIGA)." (PMID 28785375, 2017). "Notably, defects in the enzymes of the GPI biosynthetic pathway such as phosphatidylinositol glycan class A (PIGA) and phosphatidylinositol glycan class M (PIGM) cause paroxysmal nocturnal hemoglobinuria (PNH) and autosomal recessive GPI-anchor deficiency, respectively." (PMID 19832981, 2009). "Paroxysmal nocturnal hemoglobinuria (PNH) is a rare, acquired clonal hematologic disorder caused by somatic mutations in the PIGA gene of hematopoietic stem cells, leading to the absence of GPI-anchored proteins, including the complement regulators CD55 and CD59." (PMID 41002734, 2025). "Paroxysmal nocturnal hemoglobinuria (PNH) is a nonmalignant clonal hematopoietic disorder characterized by the lack of glycosylphosphatidylinositol-anchored proteins (GPI-APs) as a consequence of somatic mutations in the phosphatidylinositol glycan anchor biosynthesis class A (PIGA) gene." (PMID 37763731, 2023). "Until the last decade, only somatic PIGA mutations had been reported in patients with paroxysmal nocturnal hemoglobinuria (PNH); germline mutations had not been reported in PIGA or any other of the genes involved in GPI anchor biosynthesis and were suspected to result in embryonic lethality." (PMID 28441409, 2017).
epilepsy (5 papers, 2020 to 2024). A brain disorder characterized by episodes of abnormally increased neuronal discharge resulting in transient episodes of sensory or motor neurological dysfunction, or psychic dysfunction. "PIGA is the first step in GPI anchor synthesis and causes neurodevelopmental delay, movement disorder, and epilepsy." (PMID 38124489, 2024).
aplastic anemia (4 papers, 2018 to 2025). Anemia resulting from bone marrow failure (aplastic or hypoplastic bone marrow). "The molecular mechanisms by which the PIGA mutation leads to such immune escape have not been fully elucidated, and different hypotheses have been postulated, starting with the possibility that the PIGA mutation may affect the surface expression of the antigens putatively causing aplastic anemia." (PMID 36110036, 2023).
Hypsarrhythmia (4 papers, 2015 to 2021). Hypsarrhythmia is abnormal interictal high amplitude waves and a background of irregular spikes. "In summary, X-linked PIGA mutations present with ESp with hypsarrhythmia and profound developmental delay." (PMID 33440761, 2021). "Additionally, hypsarrhythmia EEG was reported in IGDs caused by disease-causing variants in PIGA, PIGP, and PIGW." (PMID 32612635, 2020). "Focal seizures with diffuse slow waves mixed with focal or multifocal discharges on EEG rather than infantile spasms with hypsarrhythmia, which as previously reported were often seen in our patients with PIGA mutations." (PMID 32220244, 2020). "Our cases with PIGA mutations were characterized by focal seizures with diffuse slow waves mixed with focal or multifocal discharges on EEG rather than infantile spasms with hypsarrhythmia." (PMID 32220244, 2020).
colon cancer (3 papers, 2012 to 2021). "These plasmids were then transfected, together with a Cas9 nickase pair, into a cell clone derived from a human colon cancer cell line HCT116 in which a truncating mutation had been incorporated into PIGA exon 6 (termed the HCT116-mutPIGA clone)." (PMID 34799652, 2021). "Although the incompletely polarized cell model cannot represent real pathological conditions, our results provide a new perspective for elucidating the roles of pIgA transcytosis in the wound repair of the colon tumor model." (PMID 34638806, 2021). "The constructed AAV-based PIGA targeting vector was used to infect two colon cancer cell lines HCT116 and DLD-1 and a pancreatic cancer cell line AsPC-1, all of which are of male origin." (PMID 23056640, 2012).
hemoglobinuria (3 papers, 2020 to 2022). A laboratory test result which indicates free hemoglobin in the urine. "Finally, mutational analysis of PIGA identified 124 PIG-A mutations in 92% of paroxymal nocturnal hemoglobinuria (PNH) patients, of which 101 were distinct mutations and 23 were recurrent." (PMID 33344222, 2020).
Ataxia (2 papers, 2022 to 2024). Ataxia refers to impaired coordination of voluntary muscle movement. "There are several reports that the defect in CACNA2D1 or CACNA2D2 causes developmental and epileptic encephalopathies, hypotonia, and severe cerebellar ataxia, symptoms of which can be also observed in IGDs, including PIGA deficiencies." (PMID 38225934, 2024).
congenital disorder of glycosylation (2 papers, 2024). Congenital disorder of glycosylation (CDG) is a fast growing group of inborn errors of metabolism characterized by defective activity of enzymes that participate in glycosylation (modification of proteins and other macromolecules by adding and processing of oligosaccharide side chains). "Mutations in the phosphatidylinositol glycan biosynthesis class A (PIGA) gene cause a rare, X-linked recessive congenital disorder of glycosylation." (PMID 38124489, 2024). "Constitutional mutation of PIGA is associated with the rare disorder; PIGA-related congenital disorder of glycosylation (PIGA-CDG), resulting in high mortality in childhood and a largely neurologic phenotype." (PMID 38546397, 2024). "Phosphatidylinositol glycan biosynthesis class A congenital disorder of glycosylation (PIGA-CDG) is an ultrarare, X-linked recessive disorder caused by partial loss of function mutations in the PIGA gene." (PMID 38124489, 2024).
infantile epileptic encephalopathy (2 papers, 2019 to 2021). an epileptic condition characterized by epileptiform abnormalities associated with progressive cerebral dysfunction. "Mutations in PtdIns glycan anchor biosynthesis (PIG) genes such as PIGP (MIM 617599) and PIGA (MIM 300868) can cause early infantile epileptic encephalopathy." (PMID 31413155, 2019).
infantile spasms (2 papers, 2015 to 2020). A rare epilepsy syndrome characterized by onset of epileptic spasms in infants between 2 and 12 months of age, and rarely up to 24 months. "Early onset infantile spasms appear to be a common feature of PIGA mutations, as is seen with many other defects in GPI-anchor biosynthesis." (PMID 25885527, 2015).
multiple myeloma (2 papers, 2017 to 2019). "Hybridomas that produce anti-J chain mAbs were selected by ELISA with the recombinant antigen peptide (data not shown) and by dot blot with pIgA purified from multiple myeloma patients." (PMID 31354895, 2019).
acute myeloid leukemia (1 paper, 2024). Acute myeloid leukemia (AML) is a group of neoplasms arising from precursor cells committed to the myeloid cell-line differentiation. "Poor-risk mutation carriers with AA have a 40% higher risk of clonal evolution to MDS or acute myeloid leukemia (AML) compared with patients with PIGA, BCOR, and BCORL1 mutations." (PMID 38646536, 2024).